CD4 (CD4 molecule)
Diseases named in the same sentence as CD4 in open-access papers (continued):
Sharing a sentence is not in itself a finding about the gene and the disease.
COVID-19 (continued). "Higher levels of phosphorylated CD3ζ (Tyr83) and ZAP70 (Tyr319) were detected in pseudovirus–M protein–stimulated TREM-2+CD4+ T cells from patients with COVID-19 compared with TREM-2− groups, whereas pseudovirus vector did not induce the phosphorylations of CD3ζ and ZAP70 in TREM-2+CD4+T cells." (PMID 34878838, 2021). "Regardless of whether or not they had DM, patients with severe COVID-19 had lower lymphocyte counts and percentages, CD3+ Cell counts, CD3+ CD4+ cell counts, CD3+ CD8 + cell counts, B(CD19+) cell counts than those with non-severe COVID-19 (all P < 0.05)." (PMID 33436069, 2021). "Furthermore, we also did not see any difference between severe COVID-19 and moderate COVID-19 patients in the proportion of SARS-Co-V2-specific IFNγ-producing CD4+ or CD8+ T cells expanded in vitro (p = 0.71 for CD4+, p = 0.48 for CD8+)." (PMID 33741972, 2021). "have recently shown that in COVID-19 patients, especially those critically ill, besides a negative correlation between T cell count (CD8+ and CD4+) and patient prognosis, both T cell types showed an exhaustive phenotype because of an increased expression of PD-1 and TIM-3." (PMID 34163490, 2021). "Nigeria has one of the largest numbers of people living with HIV in SSA and there is greater concern for those with low CD4 cell count, advanced disease, high viral load, and those not on antiretroviral treatment (ART) given that COVID-19 also has adverse immunological and clinical effects." (PMID 33720975, 2021). "The higher prevalence of IL-2-producing SARS-CoV-2-specific cell clones could support the predominance of CD4+, rather than CD8+, T lymphocytes as expression of immune memory in patients who overcome COVID-19." (PMID 34962970, 2021). "The frequencies of naïve (CD45RA+) and non-naïve (CD45RA–) CD4+ T cells as well as the frequencies of CD45RA−CXCR5– Th and CD45RA−CXCR5+ PD-1+ Tfh-like cells within CD4+ T cells were not significantly different in COVID-19 patients vs controls." (PMID 34614036, 2021). "The Th cells (CD3+CD4+) and Ts cells (CD3+CD8+) were significantly lower in the ICU COVID-19 patients compared to the non-ICU COVID-19 patients from the admission to hospital to day 7 (p = 0.002 and p < 0.001, respectively, for Th cells, p < 0.001 and p = 0.003, respectively, for Ts cells)." (PMID 34071149, 2021). "To assess whether the presence of S1/S2 IgG antibodies was associated with increased T cell responses, we compared spike-specific CD4+ T cells in IgG-positive and -negative patients in OTD-CoV-2pos individuals and patients with severe COVID-19." (PMID 34858405, 2021). "In this context, using multiple experimental approaches, SARS-CoV-2-specific CD4+ and CD8+ T lymphocytes against structural and non-structural regions were observed in all COVID-19 cases, even among antibody-seronegative asymptomatic and mild COVID-19 cases." (PMID 34194438, 2021). "Interestingly in the COVID-19(+) group there were positive correlations RE-LYMP with CD25 and CD45RO markers in both CD4 and CD8+ cells without correlations with markers CD38 and HLA-DR." (PMID 33419040, 2021). "Notably, the decline in CD3+ T cells, CD4+ T cells, CD8+ T cells, B cells and NK cells was more marked in critically severe patients with COVID-19 than in non-severe patients." (PMID 34123873, 2021). "In addition, the total counts of LYM subsets such as CD3+ T cells, CD4+ T cells, CD8+ T cells, and CD19+ B cells were substantially lower to both severe and non-severe COVID-19 patients." (PMID 33557779, 2021). "However, there is evidence that responsiveness to COVID-19 vaccination and the durability of vaccine-induced immunity may be dampened in non-HIV-associated immunocompromised individuals and individuals living with HIV who are non-virally suppressed and have low CD4 counts." (PMID 34992610, 2021). "In addition, scSeq of PBMCs revealed increases in cytotoxic effector CD4+ and CD8+ T cell subsets in non-severe convalescent COVID-19 patients only." (PMID 34322127, 2021).
COVID-19 (continued). "The secretion of TNF-α and IL-6 by CD4+ Th cells in the peripheral blood may not be the main reason for the significant increase in TNF-α and IL-6 in the peripheral blood of COVID-19 patients." (PMID 32976531, 2020). "Therefore, to date no study has assessed both CD4 and CD8 T-cell polyfunctionality in the COVID-19 context, especially on ICU patients." (PMID 33178207, 2020). "Several observational studies and case reports have previously indicated that individuals with well-managed HIV likely achieve COVID-19 mRNA vaccine immune responses comparable to people living without HIV, while people living with HIV (PLWH) with lower CD4 counts may have an impaired response." (PMID 39902315, 2025). "Within the T cell population, we observed higher CD4+ to CD8+ T cell ratios in Non-COVID-19, and this effect was even more pronounced in Post-Vaccination, aligning with previously reported predominance of cardiac CD4+ lymphocytic infiltrates in response to COVID-19 vaccination." (PMID 39994453, 2025). "Under N protein stimulation, convalescent COVID-19 patients had no significant changes in the total number of CD4+ T and CD8+ T cells compared with the unexposed elderly patients; meanwhile, S protein significantly decreased the percentage of CD4+ T cells in the convalescent COVID-19 patients." (PMID 38424104, 2024). "The in vitro screening was performed on total memory CD4+ and CD8+ T cells from the matched blood samples from the acute and recovery stages of the disease of 15 patients with AIDP who had distinct potential infection triggers, including SARS-CoV-2 (non-COVID-19 and post-COVID-19 GBS))." (PMID 38233524, 2024). "In summary, we have shown that spike-specific but not non-spike specific CD4+ and CD8+ T cells become more polyfunctional in previously infected individuals after mRNA vaccination, irrespective of inhibitory receptor expression and the initial severity of COVID-19." (PMID 38064569, 2023). "BAFF can promote CD4+ T cell IFN-γ production and CD8+ T cell cytotoxicity in chronic obstructive pulmonary disease, supporting the concept that it may be part of a positive feedback loop that sustains nonspecific cytotoxic lymphocyte activation in COVID-19." (PMID 36472908, 2023). "An increased number of IFN-γ expressing CD4+ T cells, CD8+ T cells, and NK cells were found in UCB from convalescent pregnant women, in levels similar to the peripheral blood levels of these immune cells seen in non-pregnant patients with mild and moderate COVID-19." (PMID 37735363, 2023). "The critical role of CD4+ T cells in promoting robust, long-lived SARS-CoV-2-specific antibody levels and in response to mRNA vaccines has been shown, including in HCT and cellular therapy recipients, in whom COVID-19 vaccines are not precluded even when B-cell aplasia occurs." (PMID 36936918, 2023). "However, in participants who did not experience any COVID-19-related symptoms or tested SARS-CoV-2 PCR-negative (despite reporting symptoms), nine out of 22 (40.9%) also exhibited a detectable SARS-CoV-2-specific CD4 T-cell response." (PMID 34140294, 2022). "By comparing intensive care unit (ICU) and non-ICU COVID-19 patients with age-matched healthy donors, we found a strong positive correlation between plasma levels of soluble FasL (sFasL) and T cell surface expression of Fas/CD95 with the propensity of T cells to die and CD4 T cell counts." (PMID 35066575, 2022). "In particular, correlation analysis between sIL-2R concentrations and the proportion of different immune cell types in COVID-19 patients suggested that sIL-2R may be a negative regulatory factor for T cells, particularly CD8+ T cells, but not CD4+ T cells, NK cells, or B cells." (PMID 35458517, 2022).
COVID-19 (continued). "Previous studies of various COVID-19 vaccines suggested that there was no statistical difference in humoral or cellular immune responses between PLWH who have viral suppression and high CD4+ T lymphocyte count (CD4 count > 200 cells/μL) and HIV-Negative Controls (HNC)." (PMID 36325346, 2022). "However, when the 17 COVID-19 survivors were divided into 9 non-severe patients and 8 severe patients, the median ratios of spike/control IFN-γ percentages of CD4+ and CD8+ T cell in the severe COVID-19 group were higher than those in the non-severe group (Figures E4A, B)." (PMID 35924252, 2022). "However, unlike pediatric COVID-19, individuals with MIS-C had reduced numbers of T cells as compared with pediatric controls, with 1.6-fold fewer CD4+ T cells (95% CI: 2.04–1.26; p = 3.28 × 10–4) and 1.42-fold fewer CD8+ T cells (95% CI: 1.87–1.07; p = 0.016)." (PMID 35275061, 2022). "Moreover, elevated levels of KIR+CD8+ T cells, but not CD4+ regulatory T cells (Tregs), were also observed in severe acute respiratory syndrome coronavirus 2 (SARS-CoV-2)– or influenza-infected patients and correlated with vasculitis in COVID-19 patients." (PMID 35258337, 2022). "We found that ALB, NLR, CD4/CD8 ratio, and eosinophil count were effective and efficient predictors of viral shedding duration, which might help discharge management for patients with non-severe COVID-19." (PMID 36620263, 2022). "Here we conduct ex vivo assays to evaluate SARS-CoV-2-specific CD4+ and CD8+ T cell responses in COVID-19 convalescent patients up to 317 days post-symptom onset (DPSO), and find that memory T cell responses are maintained during the study period regardless of the severity of COVID-19." (PMID 34193870, 2021). "In all of them demonstrated the presence of CD4+ and CD8+ T cells recognizing multiple region of nucleocapsid protein and showed that SARS-CoV-2 recovered patients (n = 23) still possess long lasting memory T cell reaction in 50% of the individuals with no history of COVID-19." (PMID 33937545, 2021). "Taken together, these results suggest that although COVID-19 vaccine responses are largely similar between nonpregnant, pregnant, and lactating individuals, the vaccine may preferentially elicit more long-lived, stem-like SARS-CoV-2–specific CD4+ T cells when administered during pregnancy." (PMID 40693463, 2025). "Therefore, this study explored whether differences existed in the T-cell phenotypes and systemic cytokine and chemokine profiles of patients admitted to a hospital with COVID-19 with and without HIV co-infection, as well as among PLWH based on their CD4+ T-cell count and HIV VL at admission." (PMID 39597537, 2024).
HIV-1 infection (1,694 papers, 1996 to 2026). The type species of lentivirus and the etiologic agent of acquired immunodeficiency syndrome (AIDS). "Transferred receptors confer cell migration and adhesion properties, and macrophage-derived membrane patches render resting CD4 + T cells susceptible to HIV-1 infection by serving as hotspots for the virus binding." (PMID 39903363, 2025). "A more comprehensive investigation into the mechanisms underlying the role of NK cells, CD4+ T-cell subsets in the immune reconstitution of PLWH is of great importance for informing the application of NK cell therapy in the treatment of HIV-1 infection." (PMID 40061947, 2025). "Multiple HIV-1 proteins modulate the activation of apoptosis, which not only assists HIV-1 infection by escaping host immune surveillance but also causes a significant decline in immune cell count, especially CD4+ T cells." (PMID 40434097, 2025). "In co-culture experiments with endothelial cells or macrophages, resting CD4+ T cells exhibit enhanced susceptibility to HIV-1 infection." (PMID 40650088, 2025). "We observed low levels of α4β7 expression on memory CD4+ T cells and invariant NK T (iNKT) cells, 2 cell types highly susceptible to HIV-1 infection, in highly exposed seronegative (HESN) compared with highly exposed seroconverter (HESC) participants." (PMID 40338667, 2025). "Advanced HIV-1 infection is associated with elevated levels of human Anelloviridae sequences in the gut virome, especially in individuals with severe immunodeficiency (CD4+ T cells < 200 cells/μL)." (PMID 40733607, 2025). "Previous studies, including, have shown that infection with Vpr-deficient (R−) virus can also induce TGF-β and enhance HIV-1 infection in both activated and resting memory CD4 + T cells." (PMID 40632811, 2025). "Emerging evidence suggests that HIV-1 infection is also associated with changes in circular RNA profiles in CD4+ T cells." (PMID 40632811, 2025). "Although their baseline transcriptional activity is low, previous studies have shown that naive CD4 T cells are susceptible to HIV-1 infection during the early stage of infection, potentially due to dysfunctional antiviral signaling in resting cells." (PMID 40838493, 2025). "This discovery links the two hallmark events of HIV-1 infection: CD4 T cell depletion and chronic inflammation." (PMID 40072080, 2025). "Myeloid cells are collectively more resistant to HIV-1 infection than CD4+ T lymphocytes, but interleukin (IL)-4 has been observed to promote macrophage susceptibility to HIV-1 infection." (PMID 40980890, 2025). "Previous research suggested that pyroptosis of quiescent cells undergoing abortive infection is a major driver of CD4+ T cell death in pathogenic HIV-1 infection." (PMID 39842407, 2025). "They included a female neonate aged 1 month who died 8 days after diagnosis, and a 43-year-old man who had underlying HIV-1 infection (with CD4 count < 20 cells/μL)." (PMID 41585781, 2025). "Overall, our results suggest that HIV-1 infection of CD4+ T cells causes an increase in the interaction between METTL3 and 14 that is associated with an increase in m6A levels." (PMID 41085277, 2025). "HIV-2 also has lower transmission rates, and while HIV-1 infection is associated with a steady decline in CD4+ T-lymphocyte counts, in HIV-2 infection, the decline is much slower and viremia levels are lower at all stages of the disease." (PMID 40507836, 2025). "HIV-1 infection is characterized by the progressive loss of CD4+ T cells, the main cellular target of infection, and a persistent state of chronic immune activation." (PMID 39842407, 2025). "Further, CCR5 expressing CD4+ T cells isolated from the EM of post-menopausal women remained more susceptible to HIV-1 infection relative to those of pre-menopausal patients." (PMID 39872519, 2024).
HIV-1 infection (continued). "Humanized mice, which contain CD4+ T cells susceptible to HIV-1 infection, have been widely used to study HIV pathogenesis, viral latency, transmission pathways, host immune responses, as well as prevention and antiviral therapies." (PMID 39192637, 2024). "For example, naïve CD4+ T cells are resistant to HIV-1 infection, while activated CD4+ T cells are more susceptible." (PMID 38400005, 2024). "In conclusion, our findings demonstrate that the susceptibility of EM CD4+ T cells to HIV-1 infection increases following menopause in conjunction with increases in several known determinants of cellular HIV infection susceptibility." (PMID 39872519, 2024). "Taken together, E2 treatment can reduce menopausal associated increases in EM CD4+ T cell HIV-1 infection susceptibility in vitro." (PMID 39872519, 2024). "This suggests that HIV-1 infection can cause selective depletion of Mtb-specific CD4+ T cell responses that are thought to be protective against TB pathogenesis." (PMID 39181733, 2024). "NK cell-mediated ADCC correlates with better clinical outcomes in HIV-1 infection, including a lower viral set point and higher CD4+ T cell counts, and has been associated with spontaneous viral control and slower progression of HIV-1 infection." (PMID 39459918, 2024). "The depletion of CD4+ T cells caused by HIV-1 infection has been linked to poor granuloma formation and a higher bacterial load." (PMID 38412342, 2024). "Functional alterations of target cells include macrophage-like migration and adhesion properties and rendering resting CD4 T cells susceptible to HIV-1 infection." (PMID 38579727, 2024). "Being predominant cells against bacterial and fungal pathogens at mucosal barriers, including the lung, CD4+ Th17 cells are highly susceptible to HIV-1 infection." (PMID 38279220, 2024). "CD4+ T cells that express short-HAVCR1 have a lower rate of HIV-1 infection in vitro that was associated with protection from HIV-1 infection in exposed seronegative individuals." (PMID 39595207, 2024). "Persistent overexpression of IFN-α/β and ISGs is a hallmark of chronic HIV-1 infection and is associated with detrimental immune activation, bystander CD4+ T-cell apoptosis, and progressive disease." (PMID 39292108, 2024). "Prior work suggests that integrin α4β7 expression increases HIV-1 infection susceptibility of cervical, gut derived, and peripheral blood CD4+ T cells." (PMID 39872519, 2024). "Our findings extend these observations by further demonstrating that the susceptibility EM CD4+ T cells to HIV-1 infection also increases following menopause." (PMID 39872519, 2024). "After controlling for changes in the expression of either receptor, both CCR5 and α4β7 expressing CD4+ T cells isolated from the EM of post-menopausal women remained more susceptible to HIV-1 infection than those isolated from pre-menopausal women." (PMID 39872519, 2024). "Given that CD4 and CCR5 are primary coreceptors of HIV-1 infection, CD4-CAR-T cells are susceptible to HIV-1 infection." (PMID 39075601, 2024). "Older age, a low nadir CD4 T cell count, a longer duration of HIV-1 infection, and co-infection with hepatitis C virus are risk factors for suboptimal CD4 T cell count recovery." (PMID 36408648, 2023). "An increased circulating IL-7 level has been reported in HIV-1 infection, associating CD4+ T lymphopenia, and an increased IL-7 production was due to a homeostatic response to T cell depletion." (PMID 37298575, 2023). "The loss of immunological cells, especially CD4+ TH cells, is the defining feature of HIV-1 infection." (PMID 36934258, 2023). "Hu-NSG-Tg(IL-15) mice were highly susceptible to HIV-1 infection and showed a decrease in the percentage of CD4+ T cells starting at 4–5 weeks post-infection and remaining low thereafter." (PMID 36851579, 2023). "The hallmark of HIV-1 infection is the progressive loss of CD4+ T cells together with activation and functional impairment." (PMID 38124099, 2023).